FGFR4 (fibroblast growth factor receptor 4)
Diseases named in the same sentence as FGFR4 in open-access papers (continued):
Sharing a sentence is not in itself a finding about the gene and the disease.
head and neck squamous cell carcinoma (11 papers, 2006 to 2024). A squamous cell carcinoma that arises from any of the following anatomic sites: lip and oral cavity, nasal cavity, paranasal sinuses, pharynx, larynx, and salivary glands. "Another study found that after cisplatin treatment intermediate and low levels of FGFR3 and FGFR4 were expressed in different head and neck squamous cell carcinoma cell lines." (PMID 39118085, 2024). "Increased risk for developing the malignant tumor was reported in prostate, however, decreased risk was observed in head and neck squamous cell carcinoma (HNSCC) and soft tissue sarcomas for FGFR4-Arg388 allele." (PMID 32154250, 2020). "The increased FGFR4 expression is correlated with worse overall survival in head and neck squamous cell carcinoma." (PMID 32781755, 2020). "To further support our findings, we evaluated FGFR4 expression by using The Cancer Genome Atlas (TCGA) Data Portal from Broad GDAC Firehose to determine whether FGFR4 was involved in the development of head and neck squamous cell carcinoma (HNSCC)." (PMID 29221201, 2017).
Hepatic steatosis (11 papers, 2016 to 2025). Steatosis is a term used to denote lipid accumulation within hepatocytes. "To investigate the underlying mechanism mediating improved hepatic steatosis and insulin sensitivity, we assessed the expression of downstream targets of FGFR4." (PMID 36586437, 2023). "In this study, we have investigated the liver-specific role of FGFR4 on hepatic steatosis, lipid, and glucose metabolism." (PMID 36586437, 2023). "Here, we sought to investigate the contribution of liver FGFR4 on hepatic steatosis in diet-induced obese mice." (PMID 36586437, 2023). "In this study, we have investigated the role of the liver-specific FGFR4 silencing on hepatic steatosis, bile acid synthesis, and insulin resistance." (PMID 36586437, 2023). "One of the most intriguing observations following hepatic FGFR4 silencing is the improvement in liver steatosis induced by HFD feeding." (PMID 36586437, 2023). "Using N-acetylgalactosamine–conjugated siRNA, we knocked down FGFR4 specifically in the liver of mice on chow or high-fat diet and in mouse primary hepatocytes to determine the role of FGFR4 in metabolic processes and hepatic steatosis." (PMID 36586437, 2023). "Regulates gut microbial abundance/diversity,regulate BAs metabolism, BA level↓,gut-hepatic FXR/FGF15/FGFR4 axis (+),intrahepatic cholestasis-induced hepatic injury↓,attenuates hepatic steatosis and NAFLD." (PMID 36817459, 2023). "In conclusion, we show that a liver FGFR4 KD improves liver steatosis by increasing hepatic bile acid synthesis." (PMID 36586437, 2023). "The IHC results demonstrated significant increases of protein expressions of FGF19, FGFR4 and EpCAM in specimens with fatty liver, NASH, cirrhosis, and HCC compared to healthy liver tissue." (PMID 27447573, 2016). "Our serum FGF19 data consist to expressions of FGF19/FGFR4 and EpCAM in tissue distributions, and provide further evidence for FGF19 as a marker to evaluate the risk of HCC in patients with fatty liver disease." (PMID 27447573, 2016). "Previous studies have shown that a whole body FGFR4 KO in mice on HFD improves liver steatosis." (PMID 36586437, 2023). "Moreover, Igfbp2, an emerging target for insulin resistance and liver steatosis, was increased with FGFR4 KD." (PMID 36586437, 2023). "Whole-body deletion of FGFR4 improves insulin sensitivity, glucose metabolism, and liver steatosis." (PMID 36586437, 2023). "Additionally, we found that high-fat diet–induced liver steatosis and insulin resistance improved following FGFR4 knockdown." (PMID 36586437, 2023). "In the gut, FXR promotes the expression of fibroblast growth factors FGF15/19, and further activates fibroblast growth factor receptor 4 (FGFR4) and β-klotho in hepatocytes, thereby inhibiting bile acid synthesis and reducing hepatic steatosis and insulin resistance." (PMID 35211093, 2022). "A study found FGFR4 could be specifically inhibited by activating a soluble FGFR4 extracellular domain fragment in vitro, and that it suppressed steatosis and the development of fatty liver in mice." (PMID 34639207, 2021). "Liver-specific FGFR4 knockdown in mice under HFD conditions increases bile acid synthesis and improves hepatic steatosis." (PMID 40585885, 2025). "In line with liver steatosis, serum alanine transaminase was significantly increased by HFD and was partially restored by FGFR4 silencing." (PMID 36586437, 2023). "Acc-ASO, fibroblastic growth factor receptor 4 (Fgfr4)-ASO and prorenin receptor ([P]rr)-ASO can ameliorate hepatic steatosis by regulating fatty acid oxidation and lipid synthesis." (PMID 36569303, 2022). "Upregulated expression of FGFR4 was recently demonstrated in murine NASH models and patients developing HCC related to fatty liver disease." (PMID 34639207, 2021). "Although the liver FGFR4 is silenced, the beneficial effects of FGF15/19 on liver steatosis may be due to its action via FGFR4 in the intestine or FGFR1 in the liver or adipose tissue." (PMID 36586437, 2023).
Hepatic steatosis (continued). "This suggests that the improvement in liver steatosis and insulin sensitivity seen in FGFR4 KD mice are not dependent on hepatic FXR activation." (PMID 36586437, 2023). "The aim of this study is to investigate the molecular components of the signaling pathways that are responsible for the development and progression of HCC and to provide the evidence for the clinical activity of FGF19, FGFR4, and EpCAM in patients with HCC arising from fatty liver disease." (PMID 27447573, 2016). "Taken together, our findings indicate that improvement in insulin sensitivity is not a direct consequence of hepatic FGFR4 silencing but may be mediated by circulating factors such as bile acids and gut hormones or be secondary to improved liver steatosis." (PMID 36586437, 2023). "However, insulin signaling was not improved in vitro following FGFR4 KO, indicating that improved insulin signaling and Igfbp2 expression in vivo were likely a consequence of improved hepatic steatosis in these mice." (PMID 36586437, 2023).
left ventricular hypertrophy (10 papers, 2017 to 2025). Enlargement of the LEFT VENTRICLE of the heart. "Animal studies have shown that FGF23 can induce left ventricular hypertrophy (LVH) through FGFR4, and in patients higher FGF23 levels predispose to development of LVH." (PMID 40237064, 2025). "For example, in the heart, FGF23 might cause left ventricular hypertrophy in a klotho‐independent manner via FGFR4." (PMID 38050660, 2024). "Previous studies revealed that elevated levels of FGF23 induce left ventricular hypertrophy in mice through FGFR4." (PMID 38560469, 2024). "FGF23 is associated with left ventricular hypertrophy (LVH) in CKD and induces LVH via klotho-independent FGFR4-mediated activation of calcineurin/nuclear factor of activated T cells (NFAT) signaling in animal models, displaying systemic alterations possibly contributing to heart injury." (PMID 34778257, 2021). "Interestingly, the FGF23/FGFR4 axis has been extensively studied in the myocardium, and when challenged by additional chronic kidney disease or high-phosphate diet, Fgfr4−/− mice also demonstrate left ventricular hypertrophy." (PMID 32793609, 2020). "Of interest, FGFR4 inhibitors are currently being developed and tested in cancer, opening potential for downstream targeting of high FGF23 levels in CKD patients to prevent the development of left ventricular hypertrophy and heart failure [63,64▪▪]." (PMID 40237064, 2025). "High FGF23 levels can act through FGFR4 to promote pathological left ventricular hypertrophy independent of α‐klotho." (PMID 40464156, 2025).
cholangiocarcinoma (9 papers, 2016 to 2025). A carcinoma that arises from the intrahepatic biliary tree (intrahepatic cholangiocarcinoma) or from the junction, or adjacent to the junction, of the right and left hepatic ducts (hilar cholangiocarcinoma). "KLa has a role in inhibiting TGF-β1-induced EMT and FGF19/FGFR4 signaling induces EMT in cholangiocarcinoma." (PMID 29731962, 2018). "However, this tendency fade away when FGFR4 was knocked down, suggesting FGFR4 is required for the FGF19-induced EMT in cholangiocarcinoma cells." (PMID 26498355, 2016). "H3B-6527 is a small inhibitor molecule developed by H3 Biomedicine Inc for targeting FGFR4-overexpression in advanced HCC and cholangiocarcinoma (IHCC) patients." (PMID 31167419, 2019). "BLU-554, a FGFR4-specific inhibitor, is under recruiting phase by Blueprint Medicines Corp. for HCC and cholangiocarcinoma patients." (PMID 31167419, 2019). "In cholangiocarcinoma (CCA), METTL16 targets PRDM15 to regulate FGFR4 expression, promoting cell proliferation and malignant progression." (PMID 41256854, 2025).
pituitary adenomas (9 papers, 2014 to 2025). "Some data suggest that ptd-FGFR4 alters cell adhesion by a mechanism that explains the loss of reticulin, which is the hallmark of pituitary adenomas." (PMID 25505910, 2014). "In pituitary adenomas, a significant correlation was observed between high levels of FGFR4 expression and the proliferation marker Ki-67, and FGFR4 expression is more prevalent in invasive tumors." (PMID 40393028, 2025). "It is important to notice that hPTTG1 and FGFR4 overexpression was previously positively correlated with elevated Ki-67 nuclear proliferation index in pituitary adenomas (>3%)." (PMID 28382019, 2017). "Altered FGF receptor expression has been found in pituitary adenomas, and FGFR4 undergoes alternative transcription initiation in pituitary adenomas, giving rise to an oncogenic protein in pituitary adenomas of various subtypes." (PMID 25505910, 2014). "In transgenic mice, expression of a truncated FGFR4 receptor cDNA resulted in the development of lactotroph pituitary adenomas, suggesting that FGFR4 dysregulation may be a key factor in the formation of pituitary adenomas." (PMID 39765842, 2024). "The lack of influence of the germline FGFR4 p.G388R variant on disease penetrance/severity suggests that currently unknown factors drive penetrance and variable phenotype in AIPmut-positive pituitary adenomas." (PMID 26186299, 2015). "Interestingly, ptd-FGFR4 overexpression causes pituitary adenoma formation without preceding hyperplasia." (PMID 25136513, 2014). "Recent evidence indicates that CD44, CD34, PTTG, FGFR4, MMP9, E‐Cadherin, and N‐Cadherin serve as biomarkers of aggressive pituitary adenomas." (PMID 41017273, 2025). "FGFR4 is a member of the FGF family critical for pituitary organogenesis and progenitor cell proliferation during embryonic development and is widely expressed in invasive human pituitary adenomas." (PMID 41017273, 2025). "Expression of a N-terminally truncated isoform of FGFR4 (ptd FGFR4) has been found in pituitary adenomas but not in normal pituitary." (PMID 25136513, 2014). "Previously, the overexpression of fibroblast growth factor receptor-4 (FGFR4) was correlated with the proliferation marker Ki-67 and tended (but not significantly) to be found in invasive pituitary adenomas." (PMID 28382019, 2017).
pituitary tumor (9 papers, 2011 to 2025). A benign or malignant neoplasm affecting the pituitary gland. "Unlike the common sporadic pituitary lactotroph adenomas in rodents or the intermediate lobe corticomelanotroph pituitary tumors associated with several mouse models of cancer, the Fgfr4 SNP knock-in mice develop GH-producing pituitary tumors." (PMID 22174695, 2011). "Human pituitary tumors express a truncated FGFR4 isoform (ptd-FGFR4), whose transcription is initiated from an alternative downstream site." (PMID 40806692, 2025). "In a large cohort of pituitary neoplasms, strong FGFR4 protein expression was observed more frequently in larger adenomas." (PMID 40806692, 2025). "In pituitary tumors, membrane-anchored wt-FGFR4 (wild-type FGFR4) formed a complex with neural cell adhesion molecule (NCAM) and N-cadherin, imparting sensitivity to FGFR inhibitor treatment." (PMID 33482911, 2021). "Tumors with loss of FGFR2 expression and presence of a truncated isoform of FGFR4, the pituitary tumor-derived FGFR4 (pdt-FGFR4), confer invasive growth of pituitary tumor cells and contributes to downregulation of N-cadherin expression." (PMID 31817110, 2019). "Here, we examined the differential properties of the available therapeutic somatostatin analogs, octreotide and pasireotide, in pituitary tumor cells expressing the different FGFR4 isoforms." (PMID 27966451, 2017). "We identified altered FGFR4 expression in pituitary tumors due to expression of an N-terminally deleted isoform, pituitary tumor-derived FGFR4 (ptd-FGFR4) generated by alternative transcription initiation from a cryptic promoter." (PMID 22174695, 2011). "We next compared GH levels and pituitary tumor size in 64 patients with pituitary tumors and acromegaly based on their FGFR4 genotypic status." (PMID 22174695, 2011). "Furthermore, Abbass along with colleagues, reported that FGFR4 undergoes NH2-terminal truncation, resulting in a pituitary tumor-derived FGFR4 variant (ptd-FGFR4), initiated through alternative transcription initiation from a cryptic intronic promoter." (PMID 40806692, 2025). "In contrast, the truncated ptd-FGFR4 (pituitary tumor-derived FGFR4) did not associate with NCAM and interfered with N-cadherin signaling to impede cell adhesion." (PMID 33482911, 2021). "Notably, activation of N-terminal truncated isoforms for MET and FGFR4 has been previously reported before in human musculoskeletal and pituitary tumors." (PMID 33482911, 2021). "The targeted expression of ptd-FGFR4 results in pituitary tumors in transgenic mice." (PMID 23900974, 2013). "In contrast, ptd-FGFR4 is a cytoplasmic protein expressed in pituitary tumors." (PMID 22174695, 2011). "Additionally, genes known to be related to pituitary tumor aggressiveness, such as securin (PTTG1) and fibroblast growth factor receptor 4 (FGFR4), are also differentially expressed in the POMC KO mouse tumors." (PMID 32591776, 2020). "Similarly, a pituitary tumor-derived, N-terminally truncated isoform of FGF receptor-4 (ptd-FGFR4) which lacks the signal peptide and the first two extracellular Ig-like domains, possesses high transforming properties in vitro and in vivo." (PMID 23900974, 2013). "Previous studies have shown that pharmacologic inhibition of wild-type FGFR4 was not effective in arresting pituitary tumor xenografts." (PMID 22174695, 2011).
squamous cell carcinoma (9 papers, 2009 to 2025). A carcinoma arising from squamous epithelial cells. "To test the in vivo tumorigenic effects of the FGFR4-388Arg variant, we xenografted into nude mice the adenocarcinoma cell line H2009 and the squamous cell carcinoma cell line H226 overexpressing either FGFR4 variant." (PMID 29402970, 2018). "In this study, TMB-high status was more common in squamous cell carcinoma, as well as in tumors harboring mutations in NOTCH1, FGFR3, or FGFR4." (PMID 34860358, 2022). "FGFR2, FGFR3, and FGFR4 expression were elevated in squamous cell carcinoma, and a high expression of FGFR1, FGFR2, FGFR3, and FGFR4 were associated with a less aggressive phenotype." (PMID 27154171, 2016). "FGFR1 was highly expressed in adeno-/adenosquamous carcinoma (P = 0.020), while FGFR2, FGFR3, and FGFR4 expression were more prominent in squamous cell carcinoma (P < 0.001, P < 0.001, and P = 0.020, respectively)." (PMID 27154171, 2016). "FGFR1 was more highly expressed in adeno-/adenosquamous carcinoma, while FGFR2, FGFR3, and FGFR4 expression was more prominent in squamous cell carcinoma (P = 0.020, P < 0.001, P < 0.001, and P = 0.020, respectively)." (PMID 27154171, 2016). "Our results propose FGFR4 profile, measured by the Gly388Arg genotype and expression, as a novel marker of prognosis in squamous cell carcinoma of the mouth and oropharynx." (PMID 23226373, 2012).
steatosis (9 papers, 2016 to 2023). Increased lipid within the cytoplasm of cells. "There was a strong correlation between the expression of FGFR4 and steatosis degree (r = −0.642, p = 0.033), as well as a correlation with interphase inflammation (r = −0.671, p = 0.024)." (PMID 37895284, 2023). "The marked net loss in liver fat by FGF19 and NGM282 is likely mediated by the FGFR1c-βKlotho and FGFR4-βKlotho receptor complexes, as an agonistic antibody against FGFR1c-βKlotho reduces steatosis and a compound upregulating CYP7A1 increases steatosis." (PMID 30679232, 2019). "FGFR4 KD in the liver improves steatosis and metabolic disfunction and thus may be a promising therapeutic target for the treatment of NAFLD." (PMID 36586437, 2023). "The involvement of FGFR4 in steatosis arises from its activation by FGF19." (PMID 34944593, 2021). "Hence, the use of FGFR4 inhibition needs to be warranted for its use in a steatosis treatment regime." (PMID 34944593, 2021). "Thus, increased bile acid synthesis and lipid secretion into the bile may account, in part, for a decrease in steatosis with FGFR4 KD in mice on HFD." (PMID 36586437, 2023). "In the present study, we found that the intestinal FXR activation mediated FGF15 is increased in NASH mice upon BBR treatment, and the binding of FGF15 with liver-specific receptor FGFR4 may contribute to the anti-steatosis and anti-inflammatory properties of BBR." (PMID 34603061, 2021). "Steatosis score, as graded by blinded pathologist, showed severe steatosis in HFD-fed mice, which was improved following FGFR4 KD." (PMID 36586437, 2023). "Taken together, the bioactivities of FGF15 on hepatocytes, instead of alleviating lipid accumulation, was shown to up-regulate FGFR4, while compromised FGF21 worsened steatosis in hepatocytes." (PMID 34326695, 2021). "EGFR is found to regulate NAFLD at various stages, starting from steatosis to NASH, and even with regard to fibrosis, while other RTKs discussed, such as AXL, FGFR4 and VEGFR, are also found to be effective in regulating different manifestations of NAFLD." (PMID 34944593, 2021). "In vitro, silencing of FGFR4 in primary mouse hepatocytes resulted in cell autonomous upregulation of IRS1, but not in an improvement of insulin signaling, which is likely mediated by a decrease in steatosis." (PMID 36586437, 2023). "Our previous studies indicated that FGF21 played a key role in preventing the development of the major characteristics of NASH: steatosis, inflammation, and metabolic syndrome, however, the FGF15/19 mediated-FGFR4 signaling worsened NASH and even contributed to the NASH-HCC transition." (PMID 34326695, 2021).
chronic kidney disease (8 papers, 2016 to 2025). Impairment of the renal function secondary to chronic kidney damage persisting for three or more months. "In chronic kidney disease (CKD), a state of FG23 excess, FGF23 can also bind to FGFR4, independently of KL." (PMID 29085059, 2017). "On the other hand, antagonizing FGF23 or inhibiting FGFR4 may block the pro-hypertrophic effects of excess FGF23, especially relevant in conditions like chronic kidney disease (CKD) and HHD." (PMID 40362262, 2025). "Moreover FGFR4−/−, FGFR4-G385R and wildtype mice on adenine diet are characterized by similar levels of hyperphosphatemia and comparable elevations of FGF23 suggesting that FGFR4 does not substantially contribute to the regulation of serum phosphate in chronic kidney disease." (PMID 31575945, 2019).